ENO1P1 (enolase 1 pseudogene 1)
Synonyms: ENO1P
Gene: Transcribed processed pseudogene on chromosome 1 (236,483,165 to 236,484,468, forward strand). Ensembl gene ENSG00000244457.
Diseases named in the same sentence as ENO1P1 in open-access papers:
ENO1P1 is named in the same sentence as 1 disease in open-access papers, as found by Europe PMC text mining. Sharing a sentence is not in itself a finding about the gene and the disease.
ENO1P1 shares sentences with these, for which no sentence is quoted: candidiasis (1 paper).